COXFA4 (cytochrome c oxidase associated subunit FA4)
Description:
Component of the cytochrome c oxidase, the last enzyme in the mitochondrial electron transport chain which drives oxidative phosphorylation. The respiratory chain contains 3 multisubunit complexes succinate dehydrogenase (complex II, CII), ubiquinol-cytochrome c oxidoreductase (cytochrome b-c1 complex, complex III, CIII) and cytochrome c oxidase (complex IV, CIV), that cooperate to transfer electrons derived from NADH and succinate to molecular oxygen, creating an electrochemical gradient over the inner membrane that drives transmembrane transport and the ATP synthase. Cytochrome c oxidase is the component of the respiratory chain that catalyzes the reduction of oxygen to water. Electrons originating from reduced cytochrome c in the intermembrane space (IMS) are transferred via the dinuclear copper A center (CU(A)) of subunit 2 and heme A of subunit 1 to the active site in subunit 1, a binuclear center (BNC) formed by heme A3 and copper B (CU(B)). The BNC reduces molecular oxygen to 2 water molecules unsing 4 electrons from cytochrome c in the IMS and 4 protons from the mitochondrial matrix. COXFA4 is required for complex IV maintenance.
Synonyms: CI-MLRQ; NDUFA4; MLRQ; CI-9k; MRCAF1; MISTR1; MC4DN21
Tractability: Small molecule: an approved drug acts on it; a structure with a bound ligand is known; it belongs to a druggable protein family. Antibody: UniProt predicts a signal peptide or a membrane-spanning region. PROTAC: ubiquitination databases record sites on it; its protein half-life has been measured; a small molecule that binds it is known.
Target class: Enzyme; Oxidoreductase
Gene: Protein-coding gene on chromosome 7 (10,931,943 to 10,940,531, reverse strand). Ensembl gene ENSG00000189043.
Subcellular location: Mitochondrion inner membrane
Subcellular location (Human Protein Atlas): Mitochondria
Pathways (Reactome):
Metabolism: Complex IV assembly; Respiratory electron transport
Cellular responses to stimuli: Cytoprotection by HMOX1
Gene Ontology:
Molecular function: protein binding; protein-containing complex binding; NADH dehydrogenase (ubiquinone) activity
Biological process: cellular respiration; mitochondrial electron transport, cytochrome c to oxygen; mitochondrial electron transport, NADH to ubiquinone; proton transmembrane transport
Cellular component: mitochondrial inner membrane; mitochondrial membrane; mitochondrion; respiratory chain complex IV
Genetic constraint (gnomAD): Loss-of-function variants: 2 observed, 3.21 expected, observed/expected ratio (o/e) 0.62, 90% interval 0.25 to 1.69. That is too few expected variants to judge how well the gene tolerates losing a copy. Missense variants: 41 observed, 29.37 expected, observed/expected ratio (o/e) 1.4, 90% interval 1.09 to 1.79. Synonymous variants: 14 observed, 12.02 expected, observed/expected ratio (o/e) 1.17, 90% interval 0.77 to 1.76.
Gene-disease validity (ClinGen):
ClinGen rates the evidence that COXFA4 causes each of these diseases.
mitochondrial disease (autosomal recessive): Definitive.
Homologues: Orthologues: chimpanzee NDUFA4 (100% identical), macaque NDUFA4 (93% identical), guinea pig NDUFA4 (90% identical), mouse Ndufa4 (89% identical), pig NDUFA4 (89% identical), rat Ndufa4 (89% identical), zebrafish ndufa4b (74% identical), zebrafish ndufa4a (69% identical). Paralogues in human: COXFA4L2 (64% identical), COXFA4L3 (31% identical).
Diseases named in the same sentence as COXFA4 in open-access papers:
COXFA4 is named in the same sentence as 54 diseases in open-access papers, as found by Europe PMC text mining. Sharing a sentence is not in itself a finding about the gene and the disease.
COXFA4 shares sentences with these, for which no sentence is quoted: cancer (11 papers); tumor (11); colorectal cancer (8); diabetes (8); gastric cancer (8); lung carcinoma (7); Sepsis (5); clear cell renal cell carcinoma (4); Neurological Disease (4); viral infection (4); Alzheimer disease (3); breast carcinoma (3); COVID-19 (3); head and neck paraganglioma (3); infection (3); Leigh syndrome (3); neurodegenerative disease (3); Parkinson disease (3); hepatocellular carcinoma (2); Huntington disease (2); Obesity (2); pancreatic cancer (2); ZIKV infection (2); bacterial sepsis (1); bipolar disorder (1); cardiac disease (1); cardiac hypertrophy (1); cholangiocarcinoma (1); Cognitive impairment (1); colitis (1).
A further 24 diseases each share a sentence with COXFA4 in 1 paper.